CXCR4 (C-X-C motif chemokine receptor 4)
Diseases named in the same sentence as CXCR4 in open-access papers (continued):
Sharing a sentence is not in itself a finding about the gene and the disease.
osteosarcoma (continued). "Lastly, by exploring spatially distinct drug-gene interactions, we identified CXCR4 as a clinically relevant therapeutic target for metastatic osteosarcoma." (PMID 39896512, 2025). "Previous reports have also demonstrated melittin’s ability to inhibit tumor angiogenesis in osteosarcoma by modulating the SDF-1α/CXCR4 signaling pathway." (PMID 39519238, 2024). "For instance, the interaction of CXC chemokine receptors (CXCR4) with stromal cell-derived factor 1 (SDF-1) can facilitate the targeted metastasis of MSC-EVs to osteosarcoma sites." (PMID 38697996, 2024). "In osteosarcoma, PTEN loss activates AKT/CXCR4 signalling while in vivo PTEN overexpression correlates with reduced CXCR4 expression." (PMID 38704478, 2024). "They investigated CXCR4, as its suppression has been shown to reduce osteosarcoma cell invasion and metastasis." (PMID 39592467, 2024). "In osteosarcoma, VEGF expression is associated with CXCR4 expression, which is found in 67% of osteosarcomas, and the co-expression of these two proteins is linked to decreased patient survival." (PMID 38542199, 2024). "Some studies have reported a robust link between the degree of CXCR4 expression and the invasive and metastatic properties of osteosarcoma." (PMID 39015175, 2024). "This is in accordance with previous studies that have shown how macrophages are able to upregulate expression of CSC markers (CD133, CXCR4, Nanog, and Oct4) in osteosarcoma cells, thus increasing the stemness of CSCs." (PMID 37249733, 2023). "In osteosarcoma, CXCL12/CXCR4 signaling promotes cancer progression and metastasis, and CXCR4 expression is associated with poor prognosis in patients." (PMID 37025604, 2023). "A recent study reported that the LM8 cell line found in mice with osteosarcoma expressed a high CXCR4 level." (PMID 36816176, 2022). "CXCR4 expression and its effect on osteosarcoma patient’s overall survival was assessed in 8 studies that yielded a pooled HR 2.13 (95%Cl = 1.78–2.55, p < 0.001), meaning patients with high CXCR4 expression had a worse prognosis." (PMID 36816176, 2022). "Beside that, significance of CXCR4 expression on clinicopathological features and prognostic on osteosarcoma (OS) require further validation." (PMID 36816176, 2022). "CXCR4 expression in osteosarcoma cells showed that it enhances the proliferation of MG-63 cell lines and migration and inhibits apoptosis." (PMID 36816176, 2022). "They demonstrated that in osteosarcoma, CXCR4 expression was directly proportional to the histological grade of the tumour and aggressiveness." (PMID 36140541, 2022). "The leading role of hypoxia in metastatic osteosarcoma dissemination seems to be mediated by the HIF-1α-CXCR4 pathway axis, which plays a crucial role during osteosarcoma cell migration." (PMID 36232719, 2022). "Evidence demonstrating the oncogenic role of CXCR4 and a putative role as therapeutic target is present in Ewing sarcoma, osteosarcoma, rhabdomyosarcoma and synovial sarcoma." (PMID 34440844, 2021). "Accordingly, recent findings have uncovered a relationship between PTEN/Akt and CXCR4 signaling pathways in osteosarcoma." (PMID 34440844, 2021). "In osteosarcoma cases, high levels of CXCR4 mRNA and protein expression were correlated with tumor progression, metastatic disease, poor metastasis-free and overall survival." (PMID 34440844, 2021). "Up to now, this is the first report concerning combine analysis of these two putative CSC markers (CXCR4/CD133) in osteosarcomas." (PMID 31983166, 2020). "Several studies highlighted that the overexpression of CXCR4 potentiated osteosarcoma growth and lung metastasis." (PMID 32974202, 2020). "The integrated bioinformatics analysis was utilized to provide new insight into osteosarcoma development and metastasis and identified EGR1, CXCL10, MYC, and CXCR4 as potential biomarkers for prognosis of osteosarcoma." (PMID 32974202, 2020).
osteosarcoma (continued). "The low expression of CXCR4 is reported to induce apoptosis of human osteosarcoma cells via PI3K-Akt signaling pathway inhibition." (PMID 30430424, 2019). "There was evidence that hypoxia promoted migration of human osteosarcoma cells by activating the HIF-1α/CXCR4 pathway." (PMID 30782196, 2019). "Laverdiere, C.; Hoang, B.H.; Yang, R.; Sowers, R.; Qin, J.; Meyers, P.A.; Huvos, A.G.; Healey, J.H.; Gorlick, R. Messenger RNA expression levels of CXCR4 correlate with metastatic behavior and outcome in patients with osteosarcoma." (PMID 31146450, 2019). "Reference 39 to “Laverdiere, C.; Hoang, B.H.; Yang, R.; Sowers, R.; Qin, J.; Meyers, P.A.; Huvos, A.G.; Healey, J.H.; Gorlick, R. Messenger RNA expression levels of CXCR4 correlate with metastatic behavior and outcome in patients with osteosarcoma." (PMID 31146450, 2019). "As a matter of fact, high CXCR4 and low SDF-1 expression by the tumor has been associated with poor overall survival in osteosarcoma and metastasis-free survival in head and neck squamous cell carcinoma." (PMID 30622535, 2018). "Hypoxia is proven to increase metastasis and progression of osteosarcoma through the HIF-1α/CXCR4 pathway in vitro." (PMID 29661211, 2018). "Recently, the chemokine CXCL12/CXCR4 signaling has been extensively investigated in osteosarcoma due to the relevance in metastasis progression and poor patient outcome." (PMID 30093974, 2018). "Along those lines, CXCR4 downregulation by overexpression of miR-613 reportedly inhibits lung metastasis of osteosarcoma orthotopically xenografted in nude mice." (PMID 30622535, 2018). "Reduced cell invasion and metastatic abilities of FOXC2 knockdown cell lines can be restored by overexpression of CXCR4, indicating that CXCR4 is a mediator of FOXC2 activity in osteosarcoma." (PMID 27634875, 2016). "The current data indicates a correlation between increased CXCR4 expression and a poor prognosis, supporting the possibility of CXCR4 inhibition as a therapeutic target for patients with osteosarcoma." (PMID 26622806, 2015). "In the osteosarcoma samples, the positive CXCR4 protein expression rate was significantly higher than the rate in the osteochondroma samples (68.75 vs. 20.00%; P<0.01)." (PMID 26622806, 2015). "CXCL12 signals through CXCR4, a seven-transmembrane G protein-coupled receptor that is expressed by normal osteoblasts and by malignant cells in osteosarcoma." (PMID 26622806, 2015). "Our study provides direct evidence that NIR fluorescence imaging using CXCR4-IR-783 visualizes osteosarcoma and its metastases." (PMID 26472699, 2015). "We also assessed the expression of CXCR4 in the two osteosarcoma cell lines using RT-PCR and found that the mRNA levels were elevated compared to controls." (PMID 25890096, 2015). "In conclusion, CXCR4-IR-783 is a promising tool for detection of high CXCR4-expressing osteosarcoma, and particularly for its metastatic lesions." (PMID 26472699, 2015). "It has been further reported that CXCR4 signaling in osteosarcoma cell lines can promote MG-63 and OS732 proliferation." (PMID 25890096, 2015). "We also found that the SDF-1/CXCR4 axis plays an important role in the proliferation of osteosarcoma cells." (PMID 25890096, 2015). "Dysregulation of Wnt/β-catenin expression is responsible for the invasion and metastasis of osteosarcoma, indicating a possible correlation between the CXCR4/CXCL12 axis and Wnt/β-catenin expression in the invasion and metastasis of osteosarcoma." (PMID 26622806, 2015). "Meanwhile, we demonstrated a higher uptake of CXCR4-IR-783 by osteosarcoma cells overexpressing CXCR4 (F5M2) than osteosarcoma cells expressing low level of CXCR4 (F4)." (PMID 26472699, 2015). "This agent exhibited superior selectivity in detection of CXCR4 expression in osteosarcoma cells both in vitro and in vivo." (PMID 26472699, 2015). "Reverse transcription polymerase chain reaction (RT-PCR) was performed to detect the expression of CXCR4 in osteosarcoma cells and BMSCs." (PMID 25890096, 2015).
osteosarcoma (continued). "An invasion assay using a Matrigel-coated invasion chamber showed that BMSCs stimulated invasion of osteosarcoma cells and that these effects were inhibited by the addition of the CXCR4 inhibitor AMD3100." (PMID 25890096, 2015). "CXCR4 was expressed in 20.00% of the osteochondroma samples collected in the current study, whereas CXCR4 was expressed in 68.75% of the osteosarcoma samples." (PMID 26622806, 2015). "CXCR4-IR-783 fluorescence was also examined in a mouse xenograft model of human osteosarcoma using NIR fluorescence microscopy and a Kodak in-vivo multispectral system." (PMID 26472699, 2015). "Immunohistochemistry was used to examine CXCR4 and β-catenin protein expression in samples obtained from osteosarcoma and osteochondroma patients." (PMID 26622806, 2015). "Taken together, therefore, these data suggest that CXCR4 is a potential therapeutic target in osteosarcoma." (PMID 25890096, 2015). "RT-qPCR data also demonstrated significantly increased levels of β-catenin (P<0.01) and CXCR4 (P<0.001) mRNA expression in osteosarcoma compared with the adjacent healthy tissue." (PMID 26622806, 2015). "In this study, we investigated the response of osteosarcoma cells to hypoxia and the expression of CXCR4 and HIF-1α in human osteosarcoma specimens and explored the roles of CXCR4 and HIF-1α in the cell migration process." (PMID 24618817, 2014). "In conclusion, this research reports the effect of hypoxia on HIF-1α expression and cell migration and the correlation of HIF-1α with CXCR4 in osteosarcoma cells." (PMID 24618817, 2014). "CTCE-9908 is a peptide antagonist for CXCR4 and has shown to inhibit both primary tumor growth and metastases in osteosarcoma and breast cancer models." (PMID 24472670, 2014). "CXCR4 mediated cell migration in a human osteosarcoma cell line involves the MEK1/2, ERK, and NFkb signaling pathways." (PMID 25514788, 2014). "Inhibition of the CXCR4/CXCL12 pathway by a peptide CXCR4 antagonist reduced the development of osteosarcoma murine lung metastases." (PMID 22518090, 2012). "OS11 is a parosteal osteosarcoma but expressed CXCR4 at the same level as the other metastatic samples, while OS18 showed a low level of CXCR4 expression." (PMID 22518090, 2012). "Recently, CXCR4 gene expression was reported to associate with both EWS and osteosarcoma metastases." (PMID 23249693, 2012). "In regards to CXCR4 inhibition for sarcoma CXCR4 inhibitors have been validated in two animal models of osteosarcoma metastasis." (PMID 21234386, 2011). "The T134 peptide, a CXCR4 inhibitor, was found to prevent the development of lung metastasis after the injection of osteosarcoma cells in a mouse model." (PMID 21234386, 2011). "In another study, administration of CTCE-9908, also a CXCR4 inhibitor, resulted in a 50% decrease in the number of metastases in mice injected with osteosarcoma cells." (PMID 21234386, 2011). "CXCR4 is expressed in 67% of osteosarcomas, with high levels of expression correlating with decreased overall survival, event-free survival, and metastasis-free survival." (PMID 21234386, 2011). "These lung metastases had more cells positive for the markers CD117, Stro-1, ABCG2, and CXCR4 than the primary bone tumor, suggesting that the osteosarcoma CSCs are the cells with an increased ability to metastasize to lung." (PMID 20979639, 2010). "In an earlier report, we described that CD4/CXCR4 positive human osteosarcoma cells stably expressing NF90ctv were able to induce transcriptional program of antiviral response genes to block HIV-1 replication." (PMID 17565699, 2007). "In osteosarcoma, the level of CXCR4 expression was inversely correlated with overall survival, but positively associated with detection of metastasis." (PMID 16819541, 2006). "Similarly, the overexpression of miR-613 supresses the growth and pulmonary metastasis of osteosarcoma by targeting CXCR4." (PMID 40307933, 2025).
osteosarcoma (continued). "Notably, the CXCR4 antagonist AMD3100 showed a synergistic effect when used in combination with anti-PD-1 antibodies in murine models of osteosarcoma." (PMID 40109854, 2025). "Furthermore, amplified miR-301a expression can prevent the suppressive action of knockdown of UCA1 in cells from osteosarcomas, a process that can be reversed by inhibiting CXCR4." (PMID 39015175, 2024). "However, the prognostic role of CXCR4 expression in patients with osteosarcoma and its correlation with the clinicopathological features have not been analyzed specifically." (PMID 36816176, 2022). "We also recently reported that losartan combined with the CXCR4 inhibitor AMD3100 could increase the efficacy of radiotherapy in a highly metastatic osteosarcoma mouse model." (PMID 33663521, 2021). "Osteosarcoma tissues were shown to be heavily infiltrated by CXCR4 positive MDSCs which could migrate toward an SDF-1 gradient." (PMID 33207697, 2020). "On the other hand, CXCR4/SDF-1 pathway might have a role in osteosarcoma tumor progression, supporting some of the sequential events that are involved in metastasis formation." (PMID 32079335, 2020). "Additionally, MMP-9 has been found to be involved in osteosarcoma cell invasion, with a highly predictive role in the development of lung metastases, especially when co-expressed with chemokine CXCR4." (PMID 32377334, 2020). "Notably, a CXCR4 antagonist was shown to synergise with anti-PD-1 antibody in inhibiting the growth of a murine model of osteosarcoma." (PMID 33207697, 2020). "CXCR4-mediated osteosarcoma growth and pulmonary metastasis is suppressed by microRNA-613." (PMID 31019537, 2019). "Recent study showed that UCA1 is able to regulate CXCR4 in osteosarcoma cells." (PMID 30940776, 2019). "In this study, we showed that FOXC2 regulates the expression of CXCR4 in osteosarcoma." (PMID 27634875, 2016). "It has also been shown that CXCR4 is expressed in osteosarcoma and may be involved in tumor lung metastases." (PMID 27634875, 2016). "In the current study, NIR fluorescence imaging using CXCR4-IR-783 detected micro-metastasis as small as 200 μm in diameter, indicating that CXCR4-targeted imaging could improve detection of CXCR4-positive osteosarcoma metastasis." (PMID 26472699, 2015). "This probe could detect both primary and micro-metastatic lung lesions of CXCR4-overexpressing osteosarcoma." (PMID 26472699, 2015). "In conclusion, the present study determined that CXCR4 and β-catenin are abnormally expressed in osteosarcoma tissues, and, therefore, may be important during osteosarcoma progression." (PMID 26622806, 2015). "CXCR4 is expressed at primary and metastatic sites of osteosarcoma." (PMID 26472699, 2015). "In addition, the current data revealed that CXCR4 and β-catenin mRNA expression were significantly higher in osteosarcoma compared with adjacent healthy tissue." (PMID 26622806, 2015). "Additionally, CXCR4 and β-catenin mRNA expression levels were measured in 16 fresh osteosarcoma and 16 adjacent healthy tissue samples using fluorescent reverse transcription-quantitative polymerase chain reaction (RT-qPCR)." (PMID 26622806, 2015). "Similarly, the RT-qPCR data identified increased CXCR4 and β-catenin mRNA expression levels in the osteosarcoma compared with adjacent control tissues." (PMID 26622806, 2015). "Higher CXCR4 mRNA levels were detected in the osteosarcoma cell lines compared to BMSCs." (PMID 25890096, 2015). "Collectively, the current results indicate that CXCR4 and β-catenin expression may be used as biomarkers to predict prognosis in patients with osteosarcoma and allow for novel therapeutic strategies to be developed." (PMID 26622806, 2015). "Additionally, the present study identified high expression of at least one of the synergistically-regulated mRNAs (CXCR4 or β-catenin) in all osteosarcoma patients." (PMID 26622806, 2015). "CXCR4 expression in the metastatic osteosarcoma tissue was demonstrated by IHC." (PMID 26472699, 2015).
osteosarcoma (continued). "The hypoxia-HIF-1α-CXCR4 pathway plays a crucial role during the migration of human osteosarcoma cells, and targeting this pathway might represent a novel therapeutic strategy for patients suffering from osteosarcoma." (PMID 24618817, 2014). "CXCR4 is a chemokine receptor for the stromal-derived factor 1 that plays an important role in the induction of chemotactic and invasive responses in several solid tumors, including osteosarcoma and RMS." (PMID 25329465, 2014). "CXCR4 may also play a role in the metastasis of osteosarcoma to the lung and neuroblastoma metastasis to the bone and bone marrow." (PMID 24259307, 2013). "KTM2 osteosarcoma lung metastases were also reduced in Balb/C mice following CXCR4 inhibition." (PMID 24058588, 2013). "In conclusion, expression of the CXCL12 scavenging receptor CXCR7 in the CXCR4-expressing human 143B osteosarcoma cell line enhances its metastatic activity in intratibial primary tumors in SCID mice that predominantly metastasize to the lung and thereby closely mimic the human disease." (PMID 24040160, 2013). "Although the number of samples analysed was moderate, our results add to the increasing number of studies linking CXCR4 to metastasis, suggesting that the expression level of CXCR4 may possibly be used as a prognostic factor in osteosarcoma." (PMID 22518090, 2012). "The role of CXCR4 in osteosarcoma metastasis has been further validated in animal models." (PMID 21234386, 2011). "In addition, there is a significant correlation in osteosarcoma between CXCR4 and expression of vascular endothelial growth factor (VEGF), a critical mediator of angiogenesis and tumor proliferation." (PMID 21234386, 2011). "Osteosarcoma cells expressing CXCR4 migrate towards a CXCL12 gradient." (PMID 21234386, 2011). "On the contrary, our results suggest that Gp120 is not directly cytotoxic to human osteoblast-like cells, and may actually induce proliferation in a small proportion of osteoblast-like osteosarcoma cells through engagement with CXCR4." (PMID 21931863, 2011). "CXCR4 expression has also been studied in melanoma, chondrosarcoma, and osteosarcoma." (PMID 20102637, 2010). "Bone also contains the chemokine ligand SDF-1 and osteosarcomas express its receptor, CXCR4." (PMID 20979639, 2010). "Importantly, osteosarcoma patients present significantly downregulated miR-613 expression, and conversely, elevated expression of miR-613 decreases the proliferation of osteosarcoma cells by directly suppressing CXCR4." (PMID 35347106, 2022). "Moreover, the inhibitory effect of UCA1 knockdown in osteosarcoma cells could be blocked by overexpression of miR-301a, but reversed by CXCR4 inhibition." (PMID 34130697, 2021). "Therefore, inhibition of CXCR4 in osteosarcoma decreases invasion and MMP1 expression." (PMID 32863948, 2020). "However, these two osteosarcoma cell lines showed a higher expression of CXCR4 compared to BMSCs." (PMID 25890096, 2015). "Consistent with our observations from TCGA and GTEx, most hub genes—including PLEK, CYBB, CXCR4, and ITGAM—were significantly upregulated in osteosarcoma samples compared to normal controls." (PMID 40895569, 2025). "When the oxygen tension is low, stromal cell-derived factor 1 (SDF-1), C-X-C chemokine receptor type 4 (CXCR4), and HIF-1α expressions are enhanced in MSCs and osteosarcoma cells." (PMID 40137351, 2025). "In osteosarcoma cell lines, inhibition of the CXCL12/CXCR4 signaling axis reduced cell proliferation in vitro and attenuated metastatic progression in vivo." (PMID 39896512, 2025). "In current clinical studies, CXCR4-modified CAR-NK promotes its migration to bone marrow and enhances its anti-multiple osteosarcoma function." (PMID 36895027, 2023). "HOS-CD4/CXCR4 is a human osteosarcoma cell line that expresses the HIV-1 receptor CD4 and its chemokine co-receptor CXCR4 and supports robust HIV-1 replication." (PMID 37509131, 2023).